NFE2L3 (NFE2 like bZIP transcription factor 3)
Diseases named in the same sentence as NFE2L3 in open-access papers (continued):
Sharing a sentence is not in itself a finding about the gene and the disease.
melanoma (4 papers, 2022 to 2023). A malignant, usually aggressive tumor composed of atypical, neoplastic melanocytes. "Here, we described the increasing transcriptional level of NFE2L3 and decreasing protein level of NRF3 in melanoma carcinogenesis while poor survival is associated with high mRNA and protein levels of NRF3." (PMID 35378827, 2022). "In the case of melanoma, low NFE2L3 mRNA expressors had a worse prognosis." (PMID 35378827, 2022). "A possible miRNA behind the observed increasing level of NFE2L3 mRNA and decreasing protein level of NRF3 could be miR-1246 that is increased in melanoma compared to normal tissues and targets NFE2L3 as a negative regulator." (PMID 35378827, 2022). "LASSO regression analysis was used to filter TFs further in order to identify a biomarker that could predict the prognosis of patients with melanoma, based on which seven TFs (TBX21, MYB, GFI1, NFE2L3, TFAP2C, HEY2, NR2F2) were selected." (PMID 37435067, 2023).
pancreatic adenocarcinoma (4 papers, 2020 to 2023). "This study showed that higher expression of NFE2L3 had poorer prognosis for OS in six tumor types, including KIRC, KIRP, brain lower grade glioma (LGG), LIHC, mesothelioma (MESO), and pancreatic adenocarcinoma (PAAD)." (PMID 35846126, 2022).
thyroid cancer (4 papers, 2019 to 2024). "Another study reported that DSCR1 functioned as a growth and metastasis suppressor of thyroid cancer in part through NFE2L3." (PMID 33827593, 2021). "The NFE2L3 messenger RNA (mRNA) is also identified to be upregulated in thyroid cancer and preinvasive testicular carcinoma samples." (PMID 31191746, 2019). "Subsequent gene chip screening and experimental analysis indicated that the downregulation of RCAN1-4 could enhance the growth and metastasis of thyroid cancer cells by upregulating NFE2L3 expression." (PMID 39149514, 2024). "In general, although both in vivo and in vitro experimental and clinical evidence suggest that inhibiting NFE2L3 expression may impede the progression of thyroid cancer, the precise mechanism by which NFE2L3 exerts its pro-tumor effects remains unclear." (PMID 39149514, 2024). "Interestingly, NFE2L3 is upregulated in human cancers, such as thyroid cancer and preinvasive testicular carcinoma." (PMID 31191746, 2019). "In thyroid cancer cells, NFE2L3 overexpression promotes cell proliferation and invasion." (PMID 31191746, 2019).
colon adenocarcinoma (3 papers, 2017 to 2024). "Further, they found that TNF-α can promote NFE2L3 transcription in colon adenocarcinoma through activating transcription factor p65 (RELA) which can bind to the first intron of NFE2L3." (PMID 39149514, 2024).
glioma (3 papers, 2021 to 2025). A benign or malignant brain and spinal cord tumor that arises from glial cells (astrocytes, oligodendrocytes, ependymal cells). "Increasing evidence indicates that NFE2L2, a protein that is homologous to the NFE2L3 transcription factor, is involved in immune evasion and is associated with immune infiltration of low-grade gliomas." (PMID 34783304, 2021). "Our findings indicated that NFE2L1 is predominantly expressed in glioma tumor tissues, with NFE2L2 exhibiting lower expression levels, whereas NFE2L3 was expressed at minimal levels." (PMID 40677211, 2025). "NFE2L3 was expressed at higher levels in single cells of AML, CML, BRCA, AST, GBM, glioma, ODG, RCC, and MEL monocyte samples however, it was expressed at lower levels in single cells of HNSCC, RB, and UM samples." (PMID 35846126, 2022).
mesothelioma (3 papers, 2022 to 2023). A usually malignant and aggressive neoplasm of the mesothelium which is often associated with exposure to asbestos. "Taken together, we speculated that NFE2L3, a novel biomarker in malignant pleural mesothelioma, can promote Th2 cell differentiation via IL-2/STAT5/NLRP3 signaling pathway in mesothelioma and many other cancers." (PMID 35664314, 2022).
osteosarcoma (3 papers, 2011 to 2024). A usually aggressive malignant bone-forming mesenchymal neoplasm, predominantly affecting adolescents and young adults. "An example of a gene upregulated in fibroblastic osteosarcoma is NFE2L3, a transcription factor which heterodimerizes with small musculoaponeurotic fibrosarcoma factors and for which a protective role was suggested in hematopoietic malignancies." (PMID 21933437, 2011).
ovarian carcinoma (3 papers, 2020 to 2024). A malignant neoplasm originating from the surface ovarian epithelium. "Furthermore, studies have linked NFE2L3 to other cancers such as lung adenocarcinoma, malignant pleural mesothelioma, and ovarian cancer, indicating its potential as a target for innovative cancer treatment approaches." (PMID 39149514, 2024).
rectal carcinoma (3 papers, 2019 to 2025). A malignant epithelial neoplasm that arises from the rectum and invades through the muscularis mucosa into the submucosa. "Through qRT-PCR experiments, we found that DHRS11, GLTP, and NFE2L3 have dysregulated expression in rectal cancer tissues." (PMID 40963625, 2025). "This study identified a TRP channel-related gene signature (BMP5, DHRS11, GLTP, NFE2L3, and TMCC3) that predicts rectal cancer prognosis and modulates tumor–immune crosstalk." (PMID 40963625, 2025).
renal carcinoma (3 papers, 2022 to 2024). A carcinoma arising from the epithelium of the renal parenchyma or the renal pelvis. "Recent studies suggested that NFE2L3 has an ideal diagnostic and prognostic value in bladder, colorectal, and renal cancers." (PMID 38514488, 2024). "However, the molecular mechanisms underlying the action of NFE2L3 in the pathogenesis and progression of renal cancer remain largely unknown." (PMID 39149514, 2024). "This trend has also been observed in renal papillary cell carcinoma, suggesting a potential role for NFE2L3 in renal cancer progression." (PMID 39149514, 2024). "Notably, the tumor-promoting effect of NFE2L3 in renal cancer was recently confirmed in vitro experiments and our ongoing work." (PMID 39149514, 2024). "Current research on NFE2L3 in renal cancer has primarily focused on analyzing sequencing data." (PMID 39149514, 2024). "Besides, NFE2L3 has a role in the regulation of the immune microenvironment in renal cancer patients." (PMID 36337840, 2022). "Notably, NFE2L3 has been identified as a key player in the development and prognosis of multiple cancer types, including colorectal, liver, thyroid, pancreatic, and renal cancers." (PMID 39149514, 2024). "Importantly, through the analysis of multiple databases, NFE2L3 was found to be strongly correlated with the prognosis of DNA methylation-driven KIRC, indicating its potential as a prognostic biomarker for renal cancer." (PMID 39149514, 2024).
ulcerative colitis (3 papers, 2022 to 2024). An inflammatory bowel disease involving the mucosal surface of the large intestine and rectum. "Our HMP2 findings showed that NFE2L3 transcripts are significantly enriched in the rectum during ulcerative colitis." (PMID 35091681, 2022). "Furthermore, analysis of RNA-seq data from the Human Microbiome Project (HMP2) showed that NFE2L3 transcript levels were higher in the rectum of patients with ulcerative colitis." (PMID 39149514, 2024). "Also, Human Microbiome Project (HMP2) data showed that NFE2L3 transcript levels are higher in the rectum of ulcerative colitis patients." (PMID 35091681, 2022).
colitis (2 papers, 2022). Inflammation of the colon. "To determine NFE2L3 function during colitis-associated carcinogenesis, we subjected adult, 8–14-week-old wild type, Nfe2l3+/– or Nfe2l3−/− mice to the well-established AOM/DSS model." (PMID 35091681, 2022). "Here, we analyzed the role of NFE2L3 in tumor development in vivo using a mouse model of colitis-associated CRC, based on the treatment with the carcinogen azoxymethane and the inflammation-inducing agent dextran sodium sulfate." (PMID 35091681, 2022). "Our studies uncovered a novel link between NFE2L3 and colitis 39 associated tumorigenesis, showing that loss of Nfe2l3 leads to a decrease in mast cell recruitment, inflammation and tumorigenesis coupled with an increase in the presence of immunosuppressive Tregs." (PMID 36289474, 2022).
colorectal tumors (2 papers, 2012 to 2022). "Concomitantly, the transcript levels of Il33 and Rab27a, both important regulators of mast cells, were reduced and increased, respectively, in the colorectal tumors of Nfe2l3−/− mice." (PMID 35091681, 2022). "For example, in our patent EP2008/010665, we described a method for the diagnosis and/or prognosis of colorectal tumour by NFE2L3 detection." (PMID 22321245, 2012).
kidney cancer (2 papers, 2022 to 2024). Primary or metastatic malignant neoplasm involving the kidney. "This information indicated that in the development of kidney cancer, the NFE2L3 expression was related to distinct gene mutations." (PMID 36337840, 2022). "The enrichment analyses revealed that NFE2L3 was associated with various immune-relevant pathways in kidney cancer and related to the infiltration ratios of 17 types of immune cells in patients with kidney cancer." (PMID 38514488, 2024). "NFE2L3 regulates the immune microenvironment and has potential prognostic value in patients with kidney cancer." (PMID 38514488, 2024). "Correspondingly, the main point of our paper is to focus on the regulatory role of NFE2L3 in the immune microenvironment of kidney cancer." (PMID 36337840, 2022).
liver cancer (2 papers, 2020 to 2024). An epithelial or non-epithelial malignant neoplasm that arises from the liver. "In addition, both cytoplasmic and nuclear β-catenin were decreased by knockdown NFE2L3, indicating NFE2L3 significantly regulated transcription of β-catenin in liver cancer cells." (PMID 33123284, 2020). "Moreover, by comparing the expression of NFE2L3 in five human liver cancer cell lines, the data suggested there was an up-regulation of NFE2L3 in cancer cells, while there was lower-expression in normal ones." (PMID 33123284, 2020). "Therefore, we tried to determine the role of NFE2L3 in the EMT of liver cancer cells." (PMID 33123284, 2020). "In vitro experiments have demonstrated that suppression of NFE2L3 inhibits cell proliferation, migration, invasion, and EMT, ultimately leading to apoptosis in liver cancer cells." (PMID 39149514, 2024). "The expression levels of NFE2L3's mRNA and protein are both upregulated in HepG2, Huh7 and MHCC97H liver cancer cell lines." (PMID 33123284, 2020).
malignant pleural mesothelioma (2 papers, 2022 to 2024). A malignant neoplasm that arises from mesothelial cells in the pleura and shows a diffuse growth pattern. "Therefore, we hypothesize that NFE2L3, a novel biomarker in malignant pleural mesothelioma, may promote the differentiation of Th2 cells through the IL-2/STAT5/NLRP3 signaling pathway in multiple cancers." (PMID 35664314, 2022).
pancreatic ductal adenocarcinoma (2 papers, 2020 to 2024). An infiltrating adenocarcinoma that arises from the epithelial cells of the pancreas. "In addition, NFE2L3 also was identified as an independent prognostic factor for the survival of patients with pancreatic ductal adenocarcinoma." (PMID 39149514, 2024).
skin cutaneous melanoma (2 papers, 2022). "In contrast, higher expression of NFE2L3 was associated with a better prognosis for OS in BLCA, skin cutaneous melanoma (SKCM), and STAD." (PMID 35846126, 2022).
squamous cell carcinoma (2 papers, 2023 to 2024). A carcinoma arising from squamous epithelial cells. "Moreover, knockout of NFE2L3 promotes the growth and malignant conversion of squamous cell carcinomas induced by 7,12-dimethylbenzo(a)anthracene and 12-O-tetradecanoylphorbol-13-acetate." (PMID 39149514, 2024).
malignant glioma (1 paper, 2025). A grade III or grade IV glioma arising from the central nervous system. "Notably, the expression of NFE2L1 was significantly elevated in malignant glioma cells and Mono/Macrophages compared with that of NFE2L2 and NFE2L3." (PMID 40677211, 2025).
metastatic melanoma (1 paper, 2022). A melanoma that has spread from its primary site to another anatomic site. "Analyzed from the TIMER2.0 database, the cases with low NFE2L3 mRNA expression had a worse survival compared to those with high mRNA expression in primary and metastatic melanoma patients." (PMID 35378827, 2022). "Also, TCGA material showed a large variance in NFE2L3 expression levels in both primary and metastatic melanoma with overlapping quartiles, and therefore, a large set of samples would be needed to recognize a significant trend." (PMID 35378827, 2022).
myopia (1 paper, 2025). "In conclusion, we have identified a novel variant, NFE2L3-p.K617T, that increases the risk of high myopia and MM in Chinese heterozygous carriers using WES and demonstrated its deleterious roles using KI mice models." (PMID 40040800, 2025). "Collectively, these findings indicate that the Nfe2l3-p.K580T variant impairs choroidal vascularization and causes scleral hypoxia and extracellular matrix remodeling, contributing to the development of myopia in mice." (PMID 40040800, 2025).
ovarian serous cystadenocarcinoma (1 paper, 2022). A malignant serous cystic epithelial neoplasm arising from the ovary. "NFE2L3 was also demonstrated to be localized in the nucleoplasm and vesicles, and the protein expression level of NFE2L3 was significantly higher in ovarian serous cystadenocarcinoma (OV), TGCT, LUSC, and CESC than in normal tissues." (PMID 35846126, 2022).
cancer (47 papers, 2012 to 2026). A tumor composed of atypical neoplastic, often pleomorphic cells that invade other tissues. "NFE2L3 has been linked to several types of cancers in humans, including colon, breast, thyroid, pancreas, and kidney." (PMID 35091681, 2022). "NFE2L3 was also identified as one of the most significantly mutated genes in tumors across 12 cancer types." (PMID 35091681, 2022). "Altered expression of NFE2L3 has been linked to cancers of the colon, breast, thyroid, pancreas, kidney, lymphatic system and liver." (PMID 35091681, 2022). "The tumor growth curve displays that NFE2L3 deficient carcinoma xenografts were slowly growing at a steady rate." (PMID 33123284, 2020). "The antibodies and Fab fragments were tested for recognition of native CTHRC1 and NFE2L3 proteins by immunoblotting analysis and enzyme-linked immunosorbent assay (ELISA) in colorectal cell lines derived from tumour and cancer tissues." (PMID 22321245, 2012). "Although the close relationship between NFE2L3 and cancers has been demonstrated, the clinical value and the underlying mechanism of NFE2L3 in cancers remain unclear." (PMID 38514488, 2024). "Although findings have suggested that NFE2L3 may be a crucial regulator of cancer progression, the underlying molecular mechanisms remain poorly understood." (PMID 38514488, 2024). "The diagnostic and prognostic value of NFE2L3 in pan-cancers was also evaluated." (PMID 35846126, 2022). "Thus, our study demonstrated that NFE2L3 expression was upregulated in a variety of cancers and was associated with poor prognosis, consistent with previous reports." (PMID 35846126, 2022). "As for its oncogenic role, NFE2L3 has been linked to a multitude of cancer hallmarks, proliferation through modulation of the cell cycle, maintaining survival by relieving proteotoxic stress, resistance to apoptosis and suppressing migration, invasion, and EMT." (PMID 35091681, 2022). "The diagnostic value of NFE2L3 expression in pan-cancer was evaluated by using the ROC curve." (PMID 35846126, 2022). "Moreover, survival analysis showed that hypermethylation of NFE2L3 was associated with good prognosis in TCGA pan-cancer (PANCAN) cohort." (PMID 35846126, 2022). "In summary, our findings suggest that one of the cancer-promoting effects of NAT10 is to promote the expression of NFE2L3, form the NAT10-NFE2L3-LASP1-Akt/GSK3β axis, and promote the occurrence and progression of ccRCC." (PMID 40169553, 2025). "A pan-cancer analysis showed that NFE2L3 is abnormally expressed in most malignancies, predominantly in the DSC." (PMID 38514488, 2024). "Recent research has revealed that NFE2L3 plays a pivotal role in cancer development, but the precise mechanisms have yet to be elucidated." (PMID 38514488, 2024). "The results of our study indicated that NFE2L3 was differentially expressed in cancers and closely related to clinical features." (PMID 38514488, 2024). "NFE2L3 belongs to the Cap ‘n’ Collar family, which plays a vital role in the cancer-promoting function by various mechanisms." (PMID 38514488, 2024). "The data from the Human Protein Atlas (HPA) annotate the abnormal expression of NFE2L3 in most tumor cell lines and cancer tissues." (PMID 38514488, 2024). "NFE2L3 is found to be abnormally expressed in cancers and regulates DSC through multiple mechanisms." (PMID 38514488, 2024). "NFE2L1 and its paralog NFE2L3 maintain the basal proteasome activity, while the simultaneous deletion of those proteins impairs proteasome function in cancer." (PMID 37662900, 2023). "The molecular function of NFE2L3 in pan-cancer was investigated through gene function enrichment analysis." (PMID 35846126, 2022). "A gene function enrichment analysis of NFE2L3 in pan-cancer was performed and the molecular mechanism of NFE2L3 in LIHC was evaluated." (PMID 35846126, 2022).